AR (androgen receptor)
Diseases named in the same sentence as AR in open-access papers (continued):
Sharing a sentence is not in itself a finding about the gene and the disease.
prostate tumors (continued). "As androgen receptor (AR) signaling is known to contribute to oxidative stress regulation, loss of AR may also affect DNA damage level and the response mechanism in oxidant and inflammatory conditions of the prostate tumor microenvironment." (PMID 38155939, 2023). "Consistent with this hypothesis, we observed that expression of genes proximal to AR sites lost in the transition from normal prostate to prostate tumor was associated with clinical outcomes among men with localized disease." (PMID 35509021, 2022). "In addition to AR splice variants, AR point mutations have been frequently detected in CRPC but rarely seen in untreated prostate tumors." (PMID 35966880, 2022). "Another splice variant, AR-V567es is also reported in prostate tumor." (PMID 31877956, 2019). "Some studies using mixed prostate tumour samples have, for example, paradoxically identified inactivating AR mutations that have been difficult to rationale in the context of almost invariable AR driven epithelial disease." (PMID 28117763, 2017). "Although multiple mechanisms underlying aberrant AR-dependent transcription have been clearly established at the molecular level, current therapeutic modalities lack the power to permanently disrupt aberrant AR activity in prostate tumor cells." (PMID 27365400, 2016). "Surprisingly, AR was also detected in the GEPFs of LNCaP and N-AR cells, suggesting that it may be associated with the Golgi compartment in prostate tumor cells." (PMID 27365400, 2016). "Indeed, although these constitutively active AR variants are already expressed in primary prostate tumors, their expression is all the more expressed in bone metastasis." (PMID 23658830, 2013). "Although the androgen receptor (AR) has a pivotal role in PrCa, mutations in the AR gene account for a small fraction of all case, underling that different genetic variations may contribute to the formation of prostate tumors." (PMID 35870994, 2022). "Thus, E2F1-mediated AR elevation may drive progression of prostate tumors with AR dependency prior to eventual loss of this dependency during NE/SC development." (PMID 34884545, 2021). "Moreover, various studies have shown that, even in a high androgen milieu, ARCC-4 inhibits prostate tumor cell proliferation and degrades enzalutamide-resistant AR with point mutations, which makes this PROTAC a potential therapeutic option in enzalutamide-resistant patients." (PMID 33805919, 2021). "In addition, the observed enrichment with the Beltran CRPC-NE signature suggests a similarity in gene expression programs with advanced cancers that lack AR activity, as neuroendocrine differentiation in prostate tumors is associated with loss of AR expression." (PMID 29334357, 2018). "Moreover, recent studies indicate that constitutively active AR variants are expressed in primary prostate tumors and may contribute to tumor progression." (PMID 23658830, 2013). "Subcutaneous xenograft tumor assays using LNCaP cells in nude mice further validated that ZMIZ2 drives prostate tumor proliferation through AR signaling." (PMID 41431399, 2026). "Although the vast majority of prostate tumors arise from the luminal lineage and remain dependent upon androgen receptor (AR) for survival, a subset of lethal prostate tumors is AR-independent." (PMID 41542660, 2026). "To our surprise, we found that having variable proportions of AR activity–high or HER2-high prostate tumor cells was a nearly universal feature of untreated (hormone-sensitive) localized prostate tumors." (PMID 40906535, 2025). "At the initial stages, prostate tumors rely on androgen receptor (AR) signaling, and treatment therefore usually consists of radical prostatectomy, radiation, or pharmacological androgen deprivation therapies." (PMID 40649790, 2025). "Prostate tumor initially requires androgen for growth, and it responds to treatment with androgen deprivation therapy and AR-targeted therapy." (PMID 40995571, 2025).
prostate tumors (continued). "Spratt and colleagues found that the AR-low, treatment-naïve primary prostate tumors that they selected for were characterized by rapid development of recurrence or metastasis." (PMID 39859392, 2025). "It should also be noted that AR amplification is a unique characteristic of prostate tumors that have been exposed to androgen deprivation, indicating that AR amplification is a consequence of hormone therapy." (PMID 40510029, 2025). "Overexpression of MYC leads to the pausing of RNA polymerase II at the promoter-proximal regions of AR-dependent genes, disrupting the AR transcriptional program promote the initiation and progression of prostate tumors." (PMID 39917165, 2025). "In order to ascertain RSPO2’s relationship with AR, we investigated its role in primary prostate tumors (TCGA, n = 489) and observed RSPO2 alterations in 9% of samples." (PMID 40711886, 2025). "While adenocarcinoma is the predominant histological variant of CRPC (CRPC-adeno), at least 20% to 25% of resistant prostate tumors undergo cellular reprogramming and shed their AR dependence." (PMID 40746825, 2025). "AR function varies widely among prostate tumors and correlates more strongly with basal/luminal status than with clinical variables." (PMID 40867349, 2025). "Prostate tumours are composed of a majority of luminal‐like androgen receptor (AR)‐positive cells interspersed with rare AR‐negative cells having neuroendocrine (NE) or stemness features." (PMID 39840448, 2025). "AR ChIP-seq peaks in human prostate tumor tissues were retrieved from GSE56288, and additional TF ChIP-seq data for PCa-related TFs were sourced from the GTRD database." (PMID 40525903, 2025). "While AR-targeted therapies provide a survival benefit for most men, prostate tumours inevitably develop mechanisms of resistance and progress to a lethal disease state termed castration-resistant prostate cancer (CRPC)." (PMID 40163908, 2025). "Key enzymes and transcription factors, such as FASN, ACLY, SREBPs, and FABPs, which are mainly regulated by androgen receptor signaling, orchestrate a lipogenic phenotype that supports prostate tumor growth and survival." (PMID 41009695, 2025). "Taken together, we show that ST3GAL1 is inversely correlated with AR signalling in prostate tumours and is upregulated in CRPC." (PMID 38448753, 2024). "In contrast, prostate tumors with high pSHP2 and pACK1 activity exhibited progressive downregulation of pY54-H3 levels and higher AR expression that correlated with disease severity." (PMID 38965223, 2024). "The phase I trial (NCT03888612) results suggested that ARV-110 is well-tolerated by the participants at doses up to 420 mg, effectively degrading AR in prostate tumors and suppressing tumor growth." (PMID 38339414, 2024). "In non-transformed prostate cell line, FOXA1, when co-expressed with HOXB13, reprograms genome-wide AR occupancy to an aggressive prostate tumour model." (PMID 39796635, 2024). "We have previously identified AR-dependent glycosylation changes in PC and have demonstrated that changes in sialyation are a feature of prostate tumours." (PMID 38448753, 2024). "As such, the niche role of stromal AR in Gli1-lineage cells to promote prostate tumor initiation and progression has been assessed using newly generated mouse models and human PCa datasets and samples." (PMID 39369165, 2024). "Here, we determine that expression of the sialyltransferase ST3Gal1 negatively correlates with AR signalling in prostate tumours." (PMID 38448753, 2024). "Overall, our simulations suggest that prolonged AR inhibition can result in changes in gene activity that is significantly different between prostate tumors from AA men and EA men." (PMID 38566104, 2024). "A significantly greater increase in AUC profiles was observed for IDH1 (34.2 vs. 9.6, P < 0.05) and SMAD (48.5 vs. 15.3, P < 0.05) after AR inhibition in prostate tumors from AA men compared to EA men." (PMID 38566104, 2024).
prostate tumors (continued). "Most prostate tumors are exquisitely dependent on androgens and the androgen receptor (AR) for growth." (PMID 39117800, 2024). "Prostate tumors with elevated expression of APUC-6 genes exhibited distinct outcomes as compared with those that were AR high and therefore represent a distinct subset of PC patients." (PMID 39207857, 2024). "CREB3L4 has been shown to directly interact with AR in LNCaP cells to increase cellular proliferation and is abundantly expressed in prostate tumour tissue." (PMID 38878676, 2024). "The two most prominent examples are the neuroendocrine-like states adopted by lung and prostate tumors that have overcome therapies that target EGFR or the androgen receptor (AR), respectively." (PMID 37832945, 2024). "Crucially, enzalutamide has been shown to act on the AR expressed in T cells to reduce T cell exhaustion, sensitising prostate tumours to ICB61." (PMID 38448753, 2024). "TRIM33 also drives prostate tumor growth by stabilizing Skp2-mediated androgen receptor degradation." (PMID 39389957, 2024). "We observed that AR gene level positively correlated with YAP1 gene level (r = 0.4959) in prostate tumors." (PMID 39149855, 2024). "Moderate/strong AR positivity was detected in testicular sex cord-stromal tumors (93.3–100%) and neoplasms of the prostate (79.3–98.7%), breast (25.0–75.5%), other gynecological tumors (0.9–100%), kidney (5.0–44.1%), and urinary bladder (5.4–24.2%)." (PMID 38790919, 2024). "In this study, we aimed to understand the effects of the loss of AR signaling upon ADT on DNA damage formation and repair activation mechanisms under oxidant and inflammatory conditions of prostate tumor microenvironment." (PMID 38155939, 2023). "ER or AR antagonists combined with ferroptosis induction inhibit the ER+ cancer or AR+ prostate tumor growth." (PMID 37580393, 2023). "The DDC inhibitor carbidopa can delay the growth of prostate tumors by reducing the activity of AR through inhibition of the co-activating effect of DDC18,20." (PMID 37872211, 2023). "In vivo experiments showed that overexpression of FEN1 significantly increased tumour growth and weakened the inhibitory effect of DTX on prostate tumour growth, while AR knockdown enhance the sensitivity of DTX to prostate tumour." (PMID 37326412, 2023). "Neuroendocrine prostate carcinoma (NEPC) accounts for less than 1% of prostate neoplasms and has extremely poorer prognosis than the typical androgen receptor pathway-positive adenocarcinoma of the prostate (ARPC)." (PMID 37240308, 2023). "Upon sonication, nanobubbles encapsulated with AR siRNA showed the lowest expression of AR mRNA in the C4-2 prostate tumor xenograft mouse model compared to the rest of the groups in the study." (PMID 36839744, 2023). "Consequently, our data suggests that YIV-818-A, RA-V, and RA-VII may possess potential to target prostate tumors bearing either wild type AR or AR-V (AR splice variants), thereby promising to substantially attenuate, if not completely nullify, the drug resistance manifested in 22RV1 cells." (PMID 37860121, 2023). "This indicated that AR knockdown further enhanced the inhibitory effect of DTX on prostate tumour growth, while FEN1 overexpression weakened this enhancement." (PMID 37326412, 2023). "Using customized high-coverage targeted NGS and ddPCR, we confirmed the copy-number neutral breakpoint to be present in every metastasis and in one of the four prostate tumor regions at varying fractions (at sub-clonal level) admixed with AR neutral cells." (PMID 37563129, 2023). "In the preclinical model evaluation, it was found that AR expression increased in prostate tumor cells deprived of androgen, which made tumor cells more likely to be dissolved by AR specific CD8+T cells." (PMID 37056394, 2023).
prostate tumors (continued). "At the molecular level, enzalutamide anchors AR in cytosol even after AR binding, thereby blocking the action of endogenous androgens in prostate tumors." (PMID 37025180, 2023). "We have described first-in-class HDAC-inhibiting compounds targeted to prostate tumors by equipping them with the additional ability to bind the androgen receptor (AR)." (PMID 36980655, 2023). "In prostate tumors, loss of CHD1 causes DNA repair defects, androgen receptor (AR) redistribution and dysfunction, chromatin instability, and transcriptional plasticity." (PMID 36776288, 2023). "This, along with the finding from targeted sequencing of AR breakpoints suggests that prostate tumors harvested at death were clonally different from other tumors present in the same patient." (PMID 37563129, 2023). "Enzalutamide is an androgen receptor antagonist commonly used to treat prostate tumours that progress following castration." (PMID 37020039, 2023). "They reported that AR activity was maintained as prostate tumors adopt alternative NE lineage, with changes in chromatin architecture guiding AR transcriptional rerouting." (PMID 36711033, 2023). "During prostate tumor cell transformation and carcinogenesis, AR activity is dysregulated, and androgen dependence and sensitivity is altered." (PMID 36937425, 2023). "Several PROTAC compounds have been reported to target androgen receptor (AR) with demonstrated efficacies toward AR protein degradation and anti-proliferation of prostate tumors in animal studies." (PMID 36893587, 2023). "The MychiPtenΔ/Δ prostate tumor displayed an ADPC histology of discernible luminal cell morphology with positive androgen receptor (AR) and cytokeratin 8 (CK8) expression." (PMID 38099497, 2023). "In contrast, CHD1 deletion is mutually exclusive with PTEN loss or TMPRSS2:ERG fusion in human prostate tumors, by crosstalk with key components in PTEN-AKT and AR signaling pathways." (PMID 36776288, 2023). "Neuroendocrine prostate carcinoma (NEPC) is a rare disease that accounts for less than 1% of prostate neoplasms and has an extremely poorer prognosis than the typical androgen receptor pathway-positive adenocarcinoma of the prostate (ARPC)." (PMID 37240308, 2023). "It should be noted that AR amplification is only seen in prostate tumors that have been exposed to androgen deprivation, indicating that AR amplification is a consequence of hormone therapy." (PMID 37894414, 2023). "These androgens then bind to the androgen receptor(s) on the prostate tumor cells, promoting and maintaining tumor growth." (PMID 37894395, 2023). "Evidence revealed that in vitro lentiviral delivery of Cas9/sgRNA affects the androgen receptor (AR) in a prostate tumor cell type." (PMID 38186450, 2023). "Recently, the pivotal role of this complex in AR-mediated prostatic tumor development was demonstrated using a compound (AU-15330) capable of selective degradation of SWI/SNF ATPases." (PMID 37025180, 2023). "Altogether, our findings suggest that MYC overexpression antagonizes the canonical AR transcriptional program and contributes to prostate tumor initiation and progression by disrupting transcriptional pause release at AR-regulated genes." (PMID 35562350, 2022). "β-catenin is a co-regulator of the AR and synergistically promotes prostate tumor cell growth through direct interaction with the AR50." (PMID 35902588, 2022). "Prostate tumor progression under ADT can occur through ligand-independent AR activation since multiple growth factors and cytokines are involved in AR transactivation." (PMID 35740556, 2022). "According to these observations, we predict that enzalutamide-resistant prostate tumors expressing AR will be more sensitive to GRT treatment as compared to those AR-negative enzalutamide-resistant prostate tumors." (PMID 35776912, 2022).
prostate tumors (continued). "Enzalutamide, a popular antiandrogen drug, inhibits the growth of castrate-resistant prostate tumors, not only by blocking androgen binding to the AR but also by obstructing AR nuclear translocation, DNA binding, and co-activator recruitment." (PMID 36060957, 2022). "We were able to devise gene lists based on AR status within specific histological contexts: normal prostate epithelium, primary prostate tumor, and metastatic prostate cancer." (PMID 35509021, 2022). "The androgen receptor (AR), a nuclear hormone receptor, contributes to the development and progression of prostate tumors and other cancers." (PMID 35053220, 2022). "Here we report high levels of AR chromatin binding heterogeneity in human primary prostate tumors, that overlap with heterogeneity observed in healthy prostate epithelium." (PMID 36450752, 2022). "Database analysis revealed that TR3 expression level is elevated in prostate tumors, and is positively, although weakly, correlated with that of AR." (PMID 35454821, 2022). "NXTAR expression epigenetically silences AR gene expression and also reduces enzalutamide-resistant prostate tumor growth." (PMID 36060957, 2022). "Androgen-receptor (AR) antagonists, enzalutamide, and abiraterone sensitized murine and human prostate tumor cells to T cell-mediated lysis." (PMID 36497086, 2022). "Castration-resistant prostate tumors also depend directly on AR, which can play a significant role in the transition from early to advanced disease and, consequently, is a valuable therapeutic target." (PMID 35456428, 2022). "We found that TR3 expression is upregulated in primary prostate tumors and that its expression level is positively, although weakly, correlated with that of AR." (PMID 35454821, 2022). "Prostate tumors progress from AR+ adenocarcinomas to AR- therapy-induced NEPC via an extensive network of transcriptional reprogramming events that lead to the expression and maintenance of neuronal features." (PMID 35447888, 2022). "In summary, our work establishes CS as an essential component of the GalNAc-containing prostate tumor glycocalyx that supports progression of AR-indifferent CRPC." (PMID 35963852, 2022). "We show that CHST11 is an AR-repressed gene and that CSA is an essential component of the prostate tumor glycocalyx that supports progression of AR-indifferent CRPC." (PMID 35963852, 2022). "For example, by using both normal and primary human prostate tissue samples, Pomerantz and colleagues showed that the AR cistrome in primary prostate tumors is distinct from that of normal tissue." (PMID 36212399, 2022). "Since androgen receptor (AR) signaling regulates the growth, survival, and proliferation of prostate tumors, the majority of PCa therapies are focused on either inhibition of androgen synthesis or blockade of androgen receptor transactivation." (PMID 35582542, 2022). "To this end, we used a gene signature of ADT resistance derived from human prostate tumors prior to treatment with ADT plus the AR inhibitor enzalutamide, in a neoadjuvant setting (NCT02430480)." (PMID 36511483, 2022). "Former study identifies MDSCs as a driver of CRPC by activating the androgen receptor pathway in prostate tumor cells, promoting cell survival and proliferation in androgen deprived conditions." (PMID 36506053, 2022). "Both AR and the αVβ6 integrin are expressed in PrCa cell-derived sEVs;6,49 and the sEV-mediated transfer of these molecules between prostate tumor subtypes as well as its impact on PrCa progression need further investigation." (PMID 35188070, 2022). "Combined, these data show that elevated CHST11 expression inversely correlates with AR signaling activity in prostate tumors." (PMID 35963852, 2022).